NRAS (NRAS proto-oncogene, GTPase)
Diseases named in the same sentence as NRAS in open-access papers (continued):
Sharing a sentence is not in itself a finding about the gene and the disease.
melanoma (continued). "Anti-PD-1 monotherapy is the standard therapy for advanced melanoma patients, including those with NRAS mutations." (PMID 34290710, 2021). "Both structureless white areas and peppering have been described more frequently in BRAF and NRAS mutated melanomas than in wild type." (PMID 34440462, 2021). "NRAS mutations are the second most frequent somatic mutations in human melanomas with a 15–38% frequency of occurrence." (PMID 34680938, 2021). "Activating RAS mutations were observed in only 10–20% of melanomas (mostly in amelanotic nodular subtypes), with NRAS mutations being the most common." (PMID 34203771, 2021). "NRAS mutations have been observed in 15–25% of melanomas and typically develop later in life after UV exposure and on the peripheral extremities." (PMID 34441278, 2021). "For melanoma patients whose tumors harbor mutation in NRAS, treatment with BRAF inhibitors is contraindicated." (PMID 34092233, 2021). "In both BRAF-mutated and NRAS-mutated melanoma cell lines, CH5126766/RO5126766 were shown to arrest the cell cycle in G1; meanwhile, SK-MEL-2 xenografts demonstrated suppression of tumor growth." (PMID 33807778, 2021). "83% (100/121) of melanoma cases had highly recurrent mutations in NRAS (27/121) or BRAF (n=73/121) that were mutually exclusive." (PMID 34804979, 2021). "Among nine patients with somatic mutation testing performed on melanoma tumors, there were four NRAS Q61R mutations, three BRAF V600E mutations, and one loss-of-function NF1 mutation." (PMID 34262818, 2021). "A preclinical study demonstrated the antitumor activity of binimetinib in 144 melanoma patient-derived cell lines, including patients with the NRAS mutation." (PMID 34830283, 2021). "They found that AhR expression was associated with the efficacy of MEK inhibitors in NRAS-mutant melanoma cell lines." (PMID 33451095, 2021). "Oncogenes linked to melanoma progression were also amplified, including NRAS, KIT and RAC1, the latter highly amplified in four patients in regions with LOH at copy numbers of 5 (patient ETH-F), 6 (patients CAS-E and SK-H) and 7 (patient CAS-F)." (PMID 33664264, 2021). "NRAS is mutated in 15–20% of all melanomas and is correlated with a more aggressive disease subtype with elevated invasive capabilities." (PMID 33917181, 2021). "Almost half of the melanoma patients harbor BRAFV600 mutations, while 30% of melanomas are driven by oncogenic NRAS mutations." (PMID 33921974, 2021). "In a series of 444 mucosal melanomas from a European population investigated by Sanger sequencing, NRAS, KIT and BRAF mutations were evenly distributed across the different mucosal melanoma subgroups." (PMID 34571863, 2021). "For the detection of the NRAS mutation in the melanoma of patient 1 (NRAS p.Q61R), a specific antibody is available." (PMID 34072863, 2021). "NRAS is mutated in 15–30% of cutaneous melanoma, and patients having NRAS mutations in melanoma are generally older (>55 years), have thicker tumors, and have inferior clinical outcomes in comparison to patients harboring BRAF mutations." (PMID 33807778, 2021). "The most prevalent form of melanoma with a mutated BRAF gene has an effective treatment, but the second most common mutation in melanoma (NRAS) leads to tumors that lack targeted therapies." (PMID 33921974, 2021). "These promising results show MEK162 to be an active targeted approach for NRAS mutations in patients with melanoma." (PMID 33807778, 2021). "In some subsets of melanomas, the activating mutations in NRAS, PIK3CA and c-KIT were also related with the hyper-activation of Akt49,50." (PMID 32968045, 2020).
melanoma (continued). "The patient with BRAF N581S melanoma (case DM077) was found to have two concurrent NRAS mutations (Q61K, Q61R) and initially demonstrated a partial response to treatment, but again progressed quickly after 4 months." (PMID 31839677, 2020). "The contrast between this observation and the association of NRAS mutation with skin with CSD suggests that detecting the UV signature mutations can help diagnose melanoma." (PMID 32429485, 2020). "At the recommended phase II dose (RP2D) of 60 mg twice-daily (bid) it has an acceptable safety profile in patients with solid tumors and potential efficacy in patients with BRAF- and/or NRAS-mutated melanoma tumors." (PMID 32610581, 2020). "Globally, 319 advanced melanoma patients undergoing molecular analysis for diagnostic classification of the BRAF/NRAS mutational status were consecutively collected in a hospital-based manner and enrolled into the study." (PMID 32751423, 2020). "Currently, genetic studies suggest that melanoma is one of the highest mutated malignancies, of which two prominent mutational events, BARF and NRAS, are observed in approximately 40–60% and 15–20% of all melanoma cases, respectively." (PMID 33005180, 2020). "Considering that NRAS mutations are present in almost one third of melanoma cases, a successful targeted therapy would be expected by now." (PMID 33072757, 2020). "Phase III trial (NEMO) compared the efficacy of MEK162 versus dacarbazine in 402 NRAS mutated, melanoma patients." (PMID 32850962, 2020). "In fact, approximately 15–25% of all metastatic tumors were shown to have NRAS mutation, and the associations of NRAS with chemotherapy resistance were shown in melanoma." (PMID 33193737, 2020). "Along with BRAF mutations, NRAS mutations are among mutations found in melanocytic and dysplastic nevi and melanomas, with high mutational load as a notable discriminant favoring the latter in diagnosis." (PMID 32429485, 2020). "On the other hand, binimetinib, a MEK1/2 inhibitor, has shown improved progression-free survival when compared to dacarbazine in patients with advanced melanoma who harbor NRAS-mutations." (PMID 32517051, 2020). "Nine of these patients had driver mutation data derived from the tumor specimen: 5/9 patients had BRAF/NRAS/KIT wild type melanoma, whereas 4/9 patients had BRAF or NRAS driver mutations identified in the tumor." (PMID 32785074, 2020). "There is also strong tissue predilection of the occurrence of RAS isoform mutations; while KRAS monopolizes pancreatic cancers, NRAS mutants dominate melanoma and AML." (PMID 31941155, 2020). "RAL was described as an inducer of proliferation in melanoma cell lines, even in the presence of NRAS and/or BRAF oncogenic mutations." (PMID 33072757, 2020). "Increasing evidence showed that KRAS mutations are closely associated with multiple cancers, including non-small-cell lung cancer, colorectal cancer, and pancreatic cancer, and NRAS mutations are present in melanomas." (PMID 32934956, 2020). "We believe that NOS- and NOX-mediated promotion of pheomelanogenesis is a pre-requisite for melanoma initiation from dysplastic nevi with BRAF/NRAS mutational background." (PMID 32850409, 2020). "HRAS mutations most often encountered in thyroid, bladder and kidney carcinomas while NRAS mutations in hepatocellular carcinoma, melanoma and haematological malignancies." (PMID 32772213, 2020). "This study investigated the efficacy and safety of pimasertib (MEK1/MEK2 inhibitor) versus dacarbazine (DTIC) in patients with untreated NRAS-mutated melanoma." (PMID 32610581, 2020). "ctDNA was less frequently detected in NRAS-mutated than in BRAF-mutated melanoma (36% and 66%, respectively)." (PMID 32664549, 2020).
melanoma (continued). "In NRAS-mutated melanomas, ICI are the only therapeutic option that proved efficacy in overall survival (OS)." (PMID 32585901, 2020). "While the prognostic significance of BRAF/NRAS mutations in melanoma is still debated, numerous studies reported that TERTprom mutations associate with poor prognosis." (PMID 32290374, 2020). "Since BRAF and NRAS mutations are usually mutually exclusive and clinical resistance to therapy involving these genes being a common issue in melanoma, finding new targets for treatment is crucial." (PMID 32276436, 2020). "BRAF and NRAS were also the more frequently mutated genes in melanoma samples as described by others, except the TERT gene which was not included in the NGS panel." (PMID 33083132, 2020). "Several years ago in vitro studies had already shown that mutated NRAS melanoma cells were sensitive to MEK inhibitors." (PMID 32850962, 2020). "Overall, the options to treat NRAS-mutated melanomas remain relatively scarce despite ongoing trials with signaling pathway targets." (PMID 32429485, 2020). "NRAS mutations are frequently detected in elderly melanoma patients, and they are preferentially found in the most aggressive histological subtype of melanoma, i.e., nodular melanoma, compared to the other histological subtypes." (PMID 33072757, 2020). "In accordance, a recent study demonstrated that the level of COX-2 expression highly influences the metastatic ability of human melanoma cells independently of the presence of NRAS or BRAF mutations." (PMID 33121001, 2020). "An analysis of mutations in the NRAS gene and the histological characteristics of melanoma were reported in 17 articles." (PMID 31274706, 2020). "The identification of the mutations in the V600 codon of BRAF (35–50% of melanomas) and Q61 codons (less frequently, the G12 or G13 codon) of NRAS (10–25% of melanomas) prompted the era of target therapy." (PMID 33233603, 2020). "Activating mutations in BRAF and NRAS in the MAPK pathway have been identified in melanomas at frequencies of 50% and 20%, respectively." (PMID 33007949, 2020). "We present the case of a 74-year-old female, who died of primary malignant melanoma of the lung involving an NRAS mutation." (PMID 32028967, 2020). "The well-known BRAF and NRAS mutations in melanoma lead to the constitutive activation of the p44/p42 MAPK pathway, which upregulates iNOS expression." (PMID 32850409, 2020). "The MEK-inhibitor Binimetinib also shows modest activity in heavily pretreated patients with NRAS-mutated melanoma with brain metastases in a pilot single-arm study." (PMID 32575838, 2020). "For instance, mutations of BRAF and NRAS target the mitogen-activated protein kinase (MAPK) pathway which is disorderly regulated in almost all melanomas." (PMID 33136551, 2020). "The MAPK pathway, which is constitutively activated by BRAF and NRAS mutations in melanoma, is positively associated with iNOS expression." (PMID 32850409, 2020). "In summary, we isolated EVs from melanoma cell lines carrying either the BRAF V600E or an NRAS mutation under normoxia and hypoxia." (PMID 32183388, 2020). "Other genetic drivers in the pathogenesis of melanoma include NRAS and neurofibromatosis 1 (NF1) mutations, but these will not be discussed in detail in this article." (PMID 32645969, 2020). "Distinct signature of the mutations can be partly explained by differential exposures to carcinogens, as is the case in Q61 NRAS mutations in melanoma linked with UV radiation, or G12C mutations in lung adenocarcinoma in association with smoking." (PMID 32524209, 2020). "Mutations in genes encoding BRAF and NRAS proteins are the most common mutations found in melanoma, where approximately 50% of melanomas harbor a BRAF mutation and about 20% carry an NRAS mutation." (PMID 32726988, 2020). "Consistently, in vivo experiments showed a decrease in melanoma growth after NRAS depletion, associated with the suppression of Ras/RAF/MEK/ERK and PI3K/Akt pathways." (PMID 33072757, 2020).
melanoma (continued). "Since KIT mutations predominate over BRAF or NRAS mutations in mucosal melanomas, this result suggests a special cooperativity between KIT gain of function and SPRED1 loss." (PMID 32455885, 2020). "This is again consistent with previous studies of CMN but inconsistent with the mutational profile of NRAS‐mutant melanoma where codons 12/13 contribute 8% to the total NRAS variants." (PMID 31111470, 2020). "NRAS mutation, described as the second most common oncogenic alteration in melanoma (20%), was associated with shorter survival in early and late stage." (PMID 36046072, 2020). "Melanoma patients harboring mutated NRAS display different characteristics compared to those harboring mutated BRAF: they are older (>55 years) and have a story of UV exposure, thicker primary tumors and a higher rate of mitosis." (PMID 32850962, 2020). "We also demonstrated the ability to detect a BCL-ABL fusion gene transcript associated with CML and reliably detected expression of both normal and mutant alleles of an NRAS SNP implicated in melanoma." (PMID 32382044, 2020). "Third, we show that phendione, as a single agent, profoundly diminishes the growth of human melanoma tumors containing BRAF or NRAS mutations." (PMID 32241802, 2020). "For example, KRAS is most commonly mutated in the Ras family in pancreas (60–90%), colorectal (30–50%), and lung (15–30%) adenocarcinomas, while NRAS has the highest mutation rate in melanoma (15–30%) and HRAS in head and neck cancer (6%)." (PMID 32524209, 2020). "Activating HRAS mutations are found in approximately 20% of Spitzoid neoplasms, while BRAF and NRAS mutations are mostly found in conventional melanomas." (PMID 33100226, 2020). "Mutations to these regulatory signals such as the oncogene NRAS or the tumor suppressor PTEN can occur alone or even in addition to other mutations in melanoma." (PMID 32429485, 2020). "(2019) in Cell recently proposed that STK19 functions as an NRAS-activating kinase and that D89N represents a gain-of-function change, which increases STK19-mediated NRAS phosphorylation, thereby increasing the malignancy of NRAS-mutated melanomas." (PMID 32531245, 2020). "In melanomas bearing NRAS mutations, targeted therapy has shown limited effectiveness and thus immune therapies and chemotherapy are generally used." (PMID 32429485, 2020). "The correlation between mutations of the NRAS gene and the location of melanoma in the limbs was significant." (PMID 31274706, 2020). "Aside from BRAF mutations, NRAS mutations have also been described in about 15% of melanoma patients, and result in the reduction of the intrinsic GTPase activity and in the constitutive activation of NRAS." (PMID 32393282, 2020). "The NF1 gene was found, to be after BRAS and NRAS, to be the third most frequently mutated in melanoma." (PMID 32605090, 2020). "This suggests a direct interaction and functional correlation between NOS and NOX, BRAF/NRAS mutations, melanoma progression, and drug-resistance." (PMID 32850409, 2020). "MEK inhibitors also determine modest benefits in terms of PFS for melanoma patients whose tumors carry missense mutations in NRAS (occurring in about 20% of melanoma cases)." (PMID 33036192, 2020). "At the same time, NRAS mutations are detected in approximately 20% of MM and are more commonly reported in melanomas developing in the skin with chronic sun exposure." (PMID 32637031, 2020). "Concluding, we show, for the first time, on a nation-wide scale and with real-life data that the frequency of a BRAF V600 mutation declines with age, whereas the frequency of an NRAS mutation increases with age in patients with advanced melanoma." (PMID 32726988, 2020).
melanoma (continued). "The most common drivers of melanoma proliferation are NRAS and BRAF mutations, constitutively activating the ERK MAPK pathway in about 80% of tumors." (PMID 32531927, 2020). "It has been found to activate the MAPK pathway by activating mutations of either NRAS or BRAF in most melanomas." (PMID 32556513, 2020). "Conversely, the most common NRAS mutations, i.e., Q61R and Q61K, affect about 20% of melanoma patients." (PMID 32858889, 2020). "We found an NRAS mutation in 14% of melanomas, and a single alteration was identified in most cases (62%)." (PMID 36046072, 2020). "A further study showed that baseline ctDNA detection was associated with poor prognosis in metastatic BRAF or NRAS-mutated melanoma patients." (PMID 33255267, 2020). "In BRAF/NRAS, wild-type melanomas and the mutations or amplifications of the c-KIT gene must be analyzed." (PMID 32054005, 2020). "The NRAS was the first oncogene identified in melanoma in 1984, and the second most prevalent after BRAF (mutation frequency of 30%)." (PMID 32850962, 2020). "For example, these results strongly suggest an implication of STAT3 in the context of the vast majority of NRAS-mutated melanoma patients who carry a codon 61 mutation and will help further validation of potential drug targets for this subgroup of patients." (PMID 31906480, 2020). "Melanocytes are known to be susceptible to neoplastic transformation by oncogenic NRAS mutants, since melanocytic neoplasias (naevi and malignant melanomas) frequently harbour NRAS Q61R or Q61K mutations." (PMID 33138083, 2020). "For example, two of the most frequent driver mutations in melanoma are the NRAS Q61R and the BRAF V600E mutations." (PMID 33207206, 2020). "The most common NRAS gene mutations are Q61R and Q61K and represent around 25% of mutations for biopsies of patients with melanoma." (PMID 31274706, 2020). "Mutations in the promoter region of the telomerase reverse transcriptase gene (TERTprom), along with mutations in BRAF/NRAS, are the most frequent genetic alterations detected in melanoma." (PMID 32290374, 2020). "In contrast to BRAF mutations, NRAS-mutant melanomas are correlated with the nodular subtype and found in CSD skin." (PMID 32429485, 2020). "NRAS mutations in melanoma tumors are responsible for the development of drug resistance in BRAF-mutated patients." (PMID 31906480, 2020). "Due to these disappointing results, the therapeutic strategies for mutated NRAS melanoma reverted on MEK inhibitors." (PMID 32850962, 2020). "In melanoma, NRAS and BRAF mutations have also been detected and used as genetic markers in tools integrating genetic and morphologic features to improve classification." (PMID 32847629, 2020). "An implementation study employing a customized Ampliseq NGS panel including 35 genes reported BRAF, TERT and NRAS as the most prevalent mutated genes in a set of 100 primary melanoma samples." (PMID 33083132, 2020). "Presently, there is evidence that NRAS mutations are associated with thicker melanomas, elevated mitotic rates, and a higher propensity for lymph node metastasis, highlighting the importance of these alterations in the clinical setting." (PMID 33072757, 2020). "For example, 90% of KRAS mutations in pancreatic ductal adenocarcinoma are at the position G12, while 90% of NRAS mutations in melanoma are at Q61." (PMID 31941155, 2020). "Comparatively, in the NEMO study, the median PFS was 2.8 months with binimetinib for patients with NRAS-mutated melanomas who were previously untreated or had progressed after previous immunotherapy." (PMID 32585901, 2020). "While several options are available for the treatment of BRAF-driven melanoma, limited targeted therapies are available for NRAS-mutated tumors, given the difficulties in directly targeting the Ras GTPase." (PMID 32517051, 2020). "It is interesting to note that the second highest MEK 6 gene score was in a melanoma found to have two concurrent NRAS mutations, Q61K and Q61R (patient DM077)." (PMID 31839677, 2020).